PIK3CA (phosphatidylinositol-4,5-bisphosphate 3-kinase catalytic subunit alpha)
Diseases named in the same sentence as PIK3CA in open-access papers (continued):
Sharing a sentence is not in itself a finding about the gene and the disease.
lipomatosis (10 papers, 2016 to 2026). A neoplastic process characterized by diffuse overgrowth of mature adipose tissue. "PIK3CA mutations drive benign adipose overgrowth in facial infiltrating lipomatosis (FIL), but the downstream molecular mechanisms remain incompletely understood." (PMID 41610323, 2026). "We detected three different PIK3CA mutations in ADSCs isolated from lipomatosis tissue from three patients, further suggesting that similar phenotypes may be caused by multiple genotypes, which is a feature of PROS." (PMID 39104411, 2024). "PIK3CA mutations drive the pathogenesis of FIL, and PIK3CA hotspot mutations may lead to more extensive infiltration of lipomatosis." (PMID 37452404, 2023). "Perineuriomatous pseudo-onion bulb proliferation is considered part of the PIK3CA-related overgrowth spectrum (PROS) and has also been described in lipomatosis of peripheral nerves with or without nerve territory overgrowth in association with PIK3CA mutations." (PMID 34438514, 2021). "Congenital infiltrating lipomatosis of the face (CILF) is a rare, congenital, nonhereditary facial overgrowth due to post-zygomatic activating mutations in PIK3CA gene." (PMID 36826055, 2023).
macrodactyly (10 papers, 2014 to 2025). "Macrodactyly is a congenital overgrowth disorder characterized by pathological adipose proliferation due to PIK3CA mutations in adipose-derived stem cells (ADSCs)." (PMID 40595500, 2025). "Our previous work demonstrated excessive adipose accumulation and increased differentiation of ADSCs in macrodactyly caused by PIK3CA mutation." (PMID 40595500, 2025). "Given the high prevalence of PIK3CA mutations in cases of isolated macrodactyly, WES is strongly recommended." (PMID 40126231, 2025). "Recently, PIK3CA mutations have been reported in macrodactyly, a rare condition related to LPN, and in other localized lipomatous overgrowth syndromes." (PMID 37067587, 2023). "Although considered a benign overgrowth, the pathogenesis of isolated macrodactyly is related to somatic PIK3CA mutations." (PMID 33557883, 2021). "No pathogenic or likely-pathogenic variant was detected in other genes currently known to be associated with macrodactyly, implicating somatic mosaicism of PIK3CA or AKT1 mutations as a predominant cause of isolated macrodactyly." (PMID 33054853, 2020). "Excessive accumulation of adipose tissue is a striking feature in macrodactyly and PIK3CA mutations were detected in adipose tissues from macrodactyly patients." (PMID 32732866, 2020). "This study reports the largest series of patients so far with PIK3CA /AKT1-associated macrodactyly, which includes 24 patients with isolated macrodactyly, all of whom carry mosaic PIK3CA or AKT1 variants." (PMID 33054853, 2020). "Somatic mutations in PIK3CA were identified in patients with macrodactyly and may be responsible for this continuous growth." (PMID 34869816, 2022). "However, now it is clear that postzygotic somatic mutations in the PIK3CA/AKT/mTOR pathway may be a cause of macrodactyly." (PMID 34869816, 2022). "We then analyzed the potential correlation between subjects’ phenotypes (i.e. macrodactyly of the upper or the lower limb, the number of affected digits, with or without syndactyly) and the domain location of variant mutations in patients carrying the PIK3CA variant." (PMID 33054853, 2020). "In this study, we utilize an NGS-based strategy to identifiy mosaic PIK3CA and AKT1 variants in a cohort of 24 isolated macrodactyly patients." (PMID 33054853, 2020). "In this study, 24 patients with macrodactyly underwent a targeted NGS-based sequencing and were identified to harbor mosaicism of either a pathogenic PIK3CA or AKT1 variant." (PMID 33054853, 2020). "However, patients with PIK3CA- or AKT1-driven macrodactyly or enlarged skeletal bones can present with either static or progressive overgrowth." (PMID 36621776, 2023). "Despite previously reported observations of PIK3CA p.Gln546Lys, p.His1047Tyr and p.Glu453Lys mutations in other PIK3CA-related overgrowth syndromes (PROS), our study represents the first time they are identified in isolated macrodactyly." (PMID 33054853, 2020).
oligodendroglioma (10 papers, 2019 to 2026). A well-differentiated (WHO grade II), diffusely infiltrating neuroglial tumor, typically located in the cerebral hemispheres. "Patient 16 with an oligodendroglioma, IDH-mutant and 1p/19q codeleted (CNS WHO grade 3) with an activating PIK3CA mutation was treated with the PIK3CA inhibitor alpelisib (allele frequency of PIK3CA mutation 33%)." (PMID 35864412, 2022). "Oligodendrogliomas showed alterations in PIK3CA (3/5) and PIK3R1 (2/5)." (PMID 35372034, 2022). "In the 23 oligodendroglioma cases, CIC (70%), PIK3CA (35%), PIK3R1 (26%), and FUBP1 (22%) were detected." (PMID 35626060, 2022).
rhabdomyosarcoma (10 papers, 2015 to 2025). A rare aggressive malignant mesenchymal neoplasm arising from skeletal muscle. "In our series, PIK3CA mutations were most commonly seen in myxoid liposarcoma (23.5%), as well as in rhabdomyosarcoma (7.4%), solitary fibrous tumor (6.3%) and UPS (5.5%)." (PMID 25906748, 2015). "PIK3CA mutations have a higher rate in rhabdomyosarcoma, where a recent study identified a frequency of 5.4% in a sample of 147 tumors." (PMID 26402468, 2015). "A genome-wide investigation, conducted in 2014 on 147 RMS samples, found alterations of the RTK-RAS-PIK3CA axis in 93% of rhabdomyosarcoma cases, and in particular, PIK3CA was mutated in 7.4% of fusion-negative samples included in the study." (PMID 40149870, 2025). "We analyzed a much larger cohort of 49 primary rhabdomyosarcoma tumor samples of various subtypes, collected over a period of 9 years, for the presence of MYOD1 (L122R), PIK3CA (H1047), and PIK3CA (E542/E545) mutations, along with immunohistochemical analysis of desmin, myogenin, and MYOD1." (PMID 27562493, 2016).
uterine corpus endometrial carcinoma (10 papers, 2014 to 2024). A endometrial carcinoma (disease) that involves the body of uterus. "Similar observations were made for a lipid kinase gene PIK3CA in uterine corpus endometrial carcinoma (UCEC: HR, 0.362; 95% CI 0.190–0.689; P = 0.002)." (PMID 31036064, 2019). "PIK3CA (P < 0.001) and PTEN mutations (P = 0.001) were associated with good outcomes in uterine corpus endometrial carcinoma." (PMID 31036064, 2019).
bladder tumors (9 papers, 2010 to 2024). "With the RAS-BC assay and mutation assays for FGFR3 and PIK3CA, we screened primary bladder tumors of 257 patients for mutations." (PMID 21072204, 2010). "With this assay and mutation assays for the FGFR3 and PIK3CA oncogenes, we screened primary bladder tumors of 257 patients and 184 recurrences from 54 patients." (PMID 21072204, 2010). "Activating mutations of PIK3CA are found in bladder tumors of all grades and stages." (PMID 27465249, 2016). "Mutations in human TERT, FGFR3, PIK3CA, and RAS genes have been proposed as potential molecular markers in bladder tumor." (PMID 27611947, 2016). "This suggests that screening bladder tumors for mutations in genes such as FGFR3, RAS and PIK3CA can be of importance for future therapy decisions." (PMID 21072204, 2010). "Recently, somatic mutations in the PIK3CA oncogene, which encodes the catalytic subunit p110α of class-IA PI3-kinase, were described in 13–27% of bladder tumors." (PMID 21072204, 2010). "Collectively, this study provides molecular evidences indicating that the gene expression rewiring occurring in primary bladder tumors, associated with increased EZH2 expression and activity and mediating the increased recurrence and progression risk, are prevented by PIK3CA-dependent signaling." (PMID 28060766, 2017).
Cowden syndrome (9 papers, 2010 to 2024). "We describe a new family with at least four individuals carrying one of the described mutations, the c.1145G>A variant of the PIK3CA gene, with clinical manifestations compatible with the Cowden syndrome spectrum." (PMID 39336800, 2024). "This gene was also linked to a minority of Cowden syndrome cases along with PIK3CA since it belongs to the same pathway as PTEN, whose mutations are causative of 85% of the cases." (PMID 28569218, 2017). "Several genes, such as EGRF, SDHB-D, PIK3CA/AKT1, and PTEN, have been linked to Cowden syndrome." (PMID 39686423, 2024). "In a study including 91 patients with clinical manifestations compatible with Cowden syndrome but without constitutional PTEN, SDHx mutations, or KLLN hypermethylation, referred to as CLS, germline mutations in the PIK3CA gene were found in eight individuals and two in the AKT gene." (PMID 39336800, 2024). "In approximately 10% of Cowden syndrome patients, the PTEN variant is absent; instead, the presence of germinal variants is detected in AKT1 (14q32.33) or PIK3CA, i.e., the genes actively involved in the same PI3K/AKT signalling pathway that is inhibited by PTEN." (PMID 35743146, 2022).
diabetes (9 papers, 2020 to 2025). "Among the top 20 core targets, 5 targets (STAT3, PIK3CA, AKT1, EGFR and VEGFA) were closely related to diabetes." (PMID 38921004, 2024). "We sequenced the PIK3CA gene in 698 samples of esophageal epithelium (covering a total of 13.96 cm2) from 10 individuals with no previous diagnosis of diabetes." (PMID 39169259, 2024). "We report the case of a 63-year-old woman with metastatic breast cancer, without pre-existing diabetes mellitus, who developed marked hyperglycemia after commencement of a novel PIK3CA inhibitor and review treatment options for PI3K inhibitor-associated hyperglycemia." (PMID 39437820, 2024).
endometrioid tumor (9 papers, 2013 to 2023). A benign, borderline, or malignant epithelial tumor of the female reproductive system characterized by the presence of glands and/or cysts lined by neoplastic cells that resemble endometrial cells. "Further studies, including more patients with charge-plus changing PIK3CA substitutions, in particular those with non-endometrioid tumors, and a better understanding of the molecular mechanism of p110α (and interaction partners) is required to confirm and extend our observations." (PMID 28860563, 2017). "In addition, different roles were found for the two isoforms in this study, as supported by the association of high mRNA levels of PIK3CB, but not PIK3CA, with markers for high proliferation (CCP score and PCNA levels), notably in endometrioid tumors." (PMID 28002804, 2017).
follicular thyroid cancers (9 papers, 2006 to 2025). "For example, mutations in PIK3CA have been more frequently associated with anaplastic and follicular thyroid cancers and to a lesser extent with PTC." (PMID 40725233, 2025). "In thyroid cancer, particularly follicular carcinoma, the catalytic subunit p110α encoding PI3K, encoded by the PIK3CA gene, is frequently mutated, which results in constitutive activation of PI3K and changes the conformation of its domain, increasing its catalytic activity." (PMID 40917751, 2025). "No PIK3CA variants were found in the FCDTCs analyzed in the present study; this finding is consistent with the literature, in which a low prevalence of these mutations has been reported in PTC and follicular thyroid cancer." (PMID 39420942, 2024).
rectal tumors (9 papers, 2011 to 2024). "Right-sided tumors had a higher frequency of BRAF and PIK3CA mutations compared to left-sided and rectal tumors." (PMID 30479693, 2018). "BRAF and PIK3CA mutations were more frequently noted in right-sided compared to left-sided colon and rectal tumors (chi-square, p=0.020 and p=0.018, respectively)." (PMID 30479693, 2018). "One 55-year-old female patient was found to have a dual PIK3CA and PTEN mutated rectal tumor with phenotype described previously." (PMID 28178681, 2017). "Of note, 1 female patient (age 55) with a dual PIK3CA and PTEN mutation had a rectal tumor demonstrating MSI-H and developed a solitary liver metastasis that has since been resected and treated with adjuvant FOLFOX – she is currently in remission." (PMID 28178681, 2017). "Additionally, higher PIK3CA gene expression (p = 0.0109) was noted in normal tissue compared to rectal tumors." (PMID 38891994, 2024).
thyroid tumor (9 papers, 2010 to 2025). A benign or malignant neoplasm affecting the thyroid gland. "We investigated SNP rs17849071 (minor allele G and major allele T) in PIK3CA in thyroid tumors in 503 subjects by PCR and sequencing of a region of intron 9 carrying this SNP." (PMID 23185308, 2012). "Similarly to other human cancers, the majority of PIK3CA gene mutations in thyroid neoplasms has been reported in exon 9 (helical domain) and 20 (kinase domain)." (PMID 20804548, 2010). "Heterozygous rs17849071G/T of the PIK3CA Gene in Normal Subjects and Various Thyroid Tumors (Odd Ratio in comparison with normal population)." (PMID 23185308, 2012). "Transgenic mice models show that PIK3CA (p.H1047R) and BRAF p.V600E co-mutation induce epithelial–mesenchymal transition (EMT) in the tumor, which in turn is associated with decreased mouse survival and transition from well-differentiated thyroid tumors to anaplastic carcinoma." (PMID 41175860, 2025). "To explore further the relationship between REC8 methylation and the PI3K pathway, we examined the hotspot mutations of five classical genes in the PI3K pathway, including H-RAS, K-RAS, N-RAS, PIK3CA and PTEN in 157 thyroid tumor samples." (PMID 26472282, 2015). "However, in undifferentiated ATC, the copy gain of PIK3CA may not necessarily represent genomic amplification; it may represent chromosomal aneuploidy, thus not following the relationship of rs17849071with PIK3CA amplification in differentiated thyroid tumors." (PMID 23185308, 2012).
cervical tumor (8 papers, 2014 to 2025). "Genomic profiling of human cervical tumors has revealed these to be among the most enriched for multiple PIK3CA mutations in cis or trans." (PMID 39706867, 2025). "Our cervical tumor mutational landscape shows that most mutations are found in PIK3CA (E545K, E542K) and KRAS (G12D, G13D) and others in FBXW7 (R465C, R505G, R479Q)." (PMID 26155992, 2015). "Expansion cohorts were opened for breast, endometrial, ovarian and cervical tumor types and for patients with PTEN loss and PIK3CA mutations." (PMID 24912489, 2014).
endometrial adenocarcinoma (8 papers, 2018 to 2025). "Using these models,it is shown that the mutations in Pik3ca and Pik3r1 cooperate with Pten loss to promote endometrial adenocarcinoma in mice." (PMID 37340596, 2023). "A high throughput drug screen that used a comprehensive library of up-to-date targeted agents was performed on uterine carcinosarcoma and endometrial adenocarcinoma organoids derived from patients with similar driver mutations in PIK3CA and PTEN." (PMID 32552764, 2020).
esophageal adenocarcinoma (8 papers, 2015 to 2022). A malignant tumor with glandular differentiation arising predominantly from Barrett mucosa in the lower third of the esophagus. "The frequency of PIK3CA mutations has been reported to range from 1.5 to 22.9% in ESCC, as well as in Barrett’s esophagus." (PMID 30115035, 2018). "Progress in targeted therapy in esophageal adenocarcinoma has been slow primarily due to failure of conventional markers in other gastrointestinal adenocarcinoma (KRAS, EGFR, PTEN, PIK3CA, and c-MET) to identify patients with esophageal adenocarcinoma who would respond to a targeted therapy." (PMID 28404924, 2017).
gallbladder carcinoma (8 papers, 2011 to 2025). "More commonly seen in gallbladder carcinoma, mutations in PIK3CA were present in 8% of the patients in the present study and are estimated to affect approximately 3–9% of all patients with ICC." (PMID 34945742, 2021). "Unsatisfactory results derived from the use of MET inhibitors such as cabozantinib (abnormal MET activation has been found in 12%–58% of iCCAs) PI3K/AKT/mTOR inhibitors showed exiguous responses despite 12.5% of gallbladder cancers displaying activated mutations of PIK3CA." (PMID 32423017, 2020). "Furthermore, PIK3CA mutations appear to be confined to gallbladder carcinomas among this cohort." (PMID 21303542, 2011). "Regarding gallbladder cancer (GBC) is the most common malignancy of the biliary tract, the general genetic abnormalities of PIK3CA (10%) and PTEN (2.3%) are found, especially the PIK3CA E545K mutation rate (6.15%)." (PMID 32333246, 2020).
Lynch syndrome (8 papers, 2013 to 2026). An autosomal dominant hereditary neoplastic syndrome characterized by the development of colorectal carcinoma and a high risk of developing endometrial carcinoma, gastric carcinoma, ovarian carcinoma, renal pelvis carcinoma, and small intestinal carcinoma. "In 35 dMMR cases with PIK3CA mutation, 6 cases (17.1%) were identified as Lynch syndrome." (PMID 32328187, 2020). "Weighted Gene Co-expression Network Analysis (WGCNA) revealed a gene module strongly positively correlated with Lynch syndrome, microsatellite instability (MSI) status, and PIK3CA mutations." (PMID 42209796, 2026). "Lynch syndrome and Lynch-like syndrome CRC frequently harbor not only activating ERBB2 mutations but also specific mutational patterns in PIK3CA and KRAS." (PMID 29849630, 2018). "After limiting to studies that excluded Lynch syndrome, the associations between early-onset CRC and BRAF (0.77, 0.64-0.92) and APC mutation (0.81, 0.67-0.97) were attenuated, while an inverse association with PIK3CA mutation was also observed (0.88, 0.78-0.99)." (PMID 38737895, 2024).